RNU6-304P (RNA, U6 small nuclear 304, pseudogene)
Gene: Small nuclear RNA gene on chromosome 1 (8,883,427 to 8,883,533, reverse strand). Ensembl gene ENSG00000201725.
Homologues: Orthologues: macaque U6 (87% identical), rat U6 (77% identical), dog U6 (70% identical), pig U6 (68% identical), guinea pig U6 (62% identical). Paralogues in human: RNU6-1099P (79% identical), RNU6-16P (79% identical), RNU6-35P (79% identical), RNU6-1316P (79% identical), RNU6-29P (79% identical), RNU6-1031P (78% identical), RNU6-140P (78% identical), RNU6-144P (78% identical), RNU6-25P (78% identical), RNU6-393P (78% identical), RNU6-434P (78% identical), RNU6-836P (78% identical), and 1287 more.